ERBB3 (erb-b2 receptor tyrosine kinase 3)
Diseases named in the same sentence as ERBB3 in open-access papers (continued):
Sharing a sentence is not in itself a finding about the gene and the disease.
breast cancer (continued). "ERBB3 was identified as a direct and functional target of miR-145 in HER2-positive breast cancer cells." (PMID 36059813, 2022). "Our findings demonstrate that circEPSTI1, an overexpressed circRNA in HER2-positive breast cancer, promotes the proliferation, migration, and invasion of SKBR3 and BT474 cells through the miR-145/ERBB3 axis." (PMID 36059813, 2022). "High ERBB3 mRNA gene expression is observed across all subtypes of breast cancer, although it predominates in HR-positive/HER2-negative disease suggesting a role for HER3 directed therapies in this disease." (PMID 33968735, 2021). "Neuregulin is a ligand for ErbB3, and its presence leads to ErbB2 and ErbB3 heterodimerization, resulting in reduced cytotoxicity of T-DMI in breast cancer cell lines." (PMID 33081383, 2020). "miR-205 directly targets ZEB1, ERBB3, and SIP1 proteins, and modulates breast cancer invasion and migration." (PMID 32854238, 2020). "Activation and overexpression of epidermal growth factor receptor (EGFR, also known as ErbB) family members, including EGFR (ErbB1 or HER1), HER3 (ErbB3), HER4 (ErbB4), and HER2 (ErbB2), govern multiple important cellular processes in breast cancer." (PMID 32223744, 2020). "We further analyzed TCGA BLBC breast cancer specimens using Ingenuity Pathway Analysis and found FGFR and ERBB3 RTK pathways are also enriched in ROR1-high BLBC specimens." (PMID 31137681, 2019). "MiR-148a inhibits breast cancer migration, invasion and angiogenesis by suppressing WNT-1, MMP-13, ERBB3." (PMID 29743122, 2018). "Taken together, our data indicated that the miRNA cluster (miR-125a and miR-205) targeting of erbB3 significantly enhanced anti-proliferative/anti-survival effects of trastuzumab and paclitaxel on HER2-overexpressing breast cancer cells." (PMID 30093840, 2018). "In order to determine surface expression levels of ErbB3, macrophages (BAC), MDA-MB 231 breast cancer cells, and endothelial cells (HUVEC) were labeled with an ErbB3 blocking antibody and analyzed by FACS." (PMID 29636067, 2018). "When the HRG ligand peptide binds the ErbB3 receptor in breast cancer cells, ErbB3-binding protein 1 (EBP1) is phosphorylated by ErbB3 and accumulates in the nucleus." (PMID 30339663, 2018). "The expression of miR-125b is downregulated in various human cancers including glioblastoma, prostate cancer, ovarian cancer, and breast cancer by suppressing oncogenes such as EST1, ERBB2, ERBB3, and BAK1 as its targets." (PMID 28435518, 2017). "In the human breast cancer cell line SKBR3, tyrosin kinase receptors ERBB2 and ERBB3 are downregulated by miR-125a leading to diminished cell proliferation and migration." (PMID 28445974, 2017). "This study also aimed to characterize ErbB signaling events involved in early breast cancer development by comparative phosphoproteomic analysis of HMLECs triggered with EGFR and ErbB3-specific ligands in the context of ErbB2 overexpression." (PMID 28174229, 2017). "Several previous studies have suggested that, in breast cancer cells overexpressing ErbB2/HER2, it localizes to membrane ruffles or protrusions together with its signaling partners, ErbB1/EGFR and ErbB3/HER3." (PMID 28369073, 2017). "In breast cancer, there is a direct mechanistic reason why HRG overcomes endocrine therapy in drug-tolerant HRG-positive ‘persister’ cells: ErbB3 signaling activates ER in an estrogen-independent manner." (PMID 28725482, 2017). "Given that ErbB3 is a potent driver of PI3K/Akt signaling in ductal luminal MECs and in luminal breast cancers, we examined P-Akt in mammary glands harvested at 16.5 d.p.c., L1, and L5." (PMID 28886748, 2017).
breast cancer (continued). "We previously reported that the erbB2 receptor simultaneously interacted with erbB3 and IGF-1R to form a heterotrimeric complex in trastuzumab-resistant breast cancer cells." (PMID 26621843, 2016). "Several basal miRNAs (miR-125b, miR-142, miR-152, miR-146b, miR-222, and miR-212) have also been predicted to target luminal factors that have been previously identified in breast cancer, including ERBB2, ERBB3, ERBB4, and FOXA1." (PMID 27845906, 2016). "We first confirmed ErbB2/ErbB3 hererodimerization in ErbB2-overexpressing BT-474 and MDA-MB-453 human breast cancer cells." (PMID 27531070, 2016). "The targets of the top luminal miRNAs were activators of EMT (ZEB1, ZEB2) and basal subtype transcription (IL-6, EGFR, STAT3), whereas the targets of the top basal miRNAs were involved in adipogenesis pathways and luminal breast cancer (ERBB2, ERBB3)." (PMID 27845906, 2016). "Previous studies have shown that inhibiting the PI3K/AKT pathway can lead to the up-regulation and over-activation of RTKs, such as HER3 (ErbB3), IGF-1R or IR, aimed at maintaining the PI3K pathway in equilibrium in breast cancer or NSCLC." (PMID 25654224, 2015). "In breast cancer cells, ZNF217-induced overexpression of ErbB2 and ErbB3 proteins is paired with increased phospho-FAK levels." (PMID 26431164, 2015). "While ERBB1, ERBB2 and ERBB3 are often overexpressed or activated in breast cancer, and are oncogenic, the role of ERBB4 in breast cancer is uncertain." (PMID 25516216, 2014). "Our data suggest that HRG-β1 and ErbB3 induce EMT, cancer cell migration and invasion through the PI3k/Akt-phospho-Smad2-Snail signaling pathway in SK-BR-3 and MCF7 breast cancer cells." (PMID 23937725, 2013). "In breast cancer, miR-125a and miR-125b were reported down-regulated in biopsy specimens and as tumor suppressors by mediating the ERBB2 and ERBB3 pathway or by targeting the ETS1 gene." (PMID 23321005, 2013). "In human breast cancer cell lines with amplified ERBB2 expression, depletion of ERBB3 reduces cell proliferation to the same extent as depletion of ERBB2, while loss of ERBB1 (epidermal growth factor receptor (EGFR)) does not affect proliferation." (PMID 23593223, 2013). "Our recent studies indicate that erbB3 interacts with both erbB2 and IGF-1 receptor to form a heterotrimeric complex in trastuzumab-resistant breast cancer cells." (PMID 24215614, 2013). "Thus, we have focused on studying whether inactivation of erbB3 signaling with MM-121 may specifically downregulate Survivin, and subsequently re-sensitize the otherwise resistant breast cancer cells to paclitaxel-mediated anti-proliferative/anti-survival effects and apoptosis." (PMID 24168763, 2013). "Since activation of the erbB3 signaling plays an important role in the development of trastuzumab resistance, we next studied whether MM-121 might overcome the resistance and enhance trastuzumab-mediated growth inhibition in two otherwise resistant breast cancer cell lines." (PMID 24215614, 2013). "MiR-125a over-expression impaired the anchorage-dependent growth, migration and invasion of breast cancer cells by down-regulating ERBB2 and ERBB3 in the ERBB2-dependent SKBR3 cell line." (PMID 22768249, 2012). "Specifically, the breast cancer line BT-474 (EC50 56.4±13.8 μM) expresses high levels of ErbB3 and ErbB2 and exhibits ligand-independent ErbB3 activation." (PMID 23166750, 2012). "Although research into the role of ErbB receptor signalling in breast cancer has focused primarily on EGFR and ErbB2, it is becoming increasingly clear that both ErbB3 and ErbB4 also have important roles to play in this disease." (PMID 21396094, 2011). "Interestingly, erbB3 signalling has also been implicated in mediating resistance to IGF-IR-targeted agents in hepatocellular carcinoma cells, but whether it plays a similar role in breast cancer remains to be determined." (PMID 21939528, 2011).
breast cancer (continued). "In this study, we demonstrated that the level of miR-148a in breast cancer cells MCF7 was lower than that in immortalized normal breast epithelial cells MCF10A, and ERBB3 is a direct target of miR-148a." (PMID 23554686, 2011). "Known therapeutic targets for breast cancer, such as ESR1, ERBB2 (HER2) and ERBB3 (HER3), are identified as showing bimodality in their gene expression level in breast cancer." (PMID 22053771, 2011). "In the breast cancer study, resistance to gefitinib or erlotinib, agents that act on the EGFR/HER1, was accompanied by increased tyrosine phosphorylation of ErbB3/HER3." (PMID 20670437, 2010). "In human breast cancer cells that over-express ErbB2 and have also developed resistance to tyrosine kinase inhibitor therapy, there is active PI3K/Akt via ErbB3 signaling." (PMID 19019207, 2008). "In breast cancers with amplified ERBB2, ErbB3 augments ErbB2 signaling through strong coupling to survival pathways that complement the signals emanating from ErbB2, thus allowing the cancer cells to escape from inhibition therapy." (PMID 19019207, 2008). "Aimed at translating our in vitro results to human BC, we evaluated, by IHC, α6β4, ERβ1, ErbB3, and P-AKT expression in 232 primary mammary tumors derived from patients submitted to adjuvant TAM monotherapy." (PMID 18270579, 2008). "Western blot analyses were used to determine erbB2 and erbB3 protein expression in tumor-derived cell lines (and the control SKBR-3 human breast cancer cell line)." (PMID 16168116, 2005). "Briefly, the surface pool of Integrin β1 on the luminal breast cancer (BRCA) cell line, MCF7, was labeled on ice with an Alexa 488–conjugated antibody, and allowed to internalize for 15 min at 37°C, prior to fixation and immunolabeling of endogenous ErbB3." (PMID 41348103, 2026). "Over-expression of ERBB3 may indicate a reliance on HER3-driven signaling loops in SET tumors, analogous to certain breast cancer subtypes." (PMID 41155518, 2025). "ErbB3 over-expression and the consequent activation of PI3K/Akt signaling lead to the development of resistance to tyrosine kinase inhibitors such as gefitinib in ErbB2 over-expressed breast cancers." (PMID 35319011, 2022). "In this study, we investigated the potential role of NRG1/ERBB3/ERBB2 signaling in different clinical and molecular subtypes of breast cancers, by combining metanalysis on patients’ survival and gene expression, and by exploring in vitro potential effects induced by the activation of this pathway." (PMID 35406375, 2022). "In addition, SORL1 expression was higher in tumors exhibiting high ERBB3 and ERBB2 expression (breast cancer patient data from the METABRIC study on the cBioportal database)." (PMID 33420373, 2021). "Our data also revealed upregulation of not only ERBB2, but also ERBB3 and ERBB4 in breast cancer." (PMID 31620367, 2019). "Further studies revealed that entinostat induced expression of miR-125a, miR-125b, and miR-205, all of which were reported to directly target the 3’UTR of erbB3 mRNA, and the three miRNAs acted in concert to inhibit HER3 protein translation in HER2-overexpressing breast cancer cells." (PMID 30093840, 2018). "In MCF-7 breast cancer cells EGCG inhibited the phosphorylation of ErbB2 and ErbB3 and suppressed the MAPK pathway, while in mammary tumor NF639 and SMF cells EGCG reportedly decreased cell proliferation, phosphorylation of ErbB2/neu and inhibited the NF-κB and MAPK pathways." (PMID 30597838, 2018). "For the UBC-TAM Series univariate analysis, favorable prognostic associations for breast-cancer-specific survival (BCSS) were detected for non-silent mutations in MAP3K1, ERBB3, XBP1, and PIK3CA." (PMID 30181556, 2018). "In the dataset of 50 breast cancer lines TF expression clustered with higher levels of basal-marker vimentin, keratin KRT5/14 and caveolin-1 (CAV1) but lower levels of luminal-marker keratin KRT8/18, ERBB3 and ESR1." (PMID 28938620, 2017).
breast cancer (continued). "This is in agreement with recent reports of ERBB3/HER2 amplifications and mutations in breast cancer brain metastasis that are absent in primary tumors." (PMID 29164052, 2017). "Alcohol exposure caused a drastic increase in the GFR (ErbB1 or HER1), ErbB2 (HER2), ErbB3 (HER3 CSC population and mammosphere formation in breast cancer cells overexpressing ErbB2, but it has a modest effect on breast cancer cells expressing low levels of ErbB2." (PMID 29156633, 2017). "Overall, these data indicate that miR-125a may counteract proliferation and invasion of breast cancer cells through the downregulation of ERBB2, ERBB3, and/or HuR." (PMID 28445974, 2017). "The suppression of ERBB2 by siRNA in tamoxifen-resistant breast cancer cells resulted in a decrease in the proliferative ability of the cells, which reconfirms the involvement of the ERBB2/ERBB3 pathways in the development of chemoresistance to breast cancer cells." (PMID 29299178, 2017). "Besides, Trastuzumab blocks the HER2-HER3(ERBB3) interaction and is used to treat breast cancers with HER2 overexpression, although some of these cancers develop trastuzumab resistance." (PMID 29322925, 2017). "UCA1 binding to miR-143 was proved in breast cancer, where UCA1 was able to modulate cell growth and apoptosis by downregulating miR-143: this in turn led to upregulation of BCL2 (BCL2, apoptosis regulator) and ERBB3 (erb-b2 receptor tyrosine kinase 3)." (PMID 29147648, 2017). "SUM149 cells were isolated from an inflammatory breast cancer patient whose tumor was defined as “triple negative” but which nevertheless in our hands expressed detectable basal levels of ERBB1, ERBB2, ERBB3, and ERBB4 by immuno-fluorescence of cells fixed in situ." (PMID 27379204, 2016). "The lethal interaction between ERBB1/2/4 inhibitors and ruxolitinib was not only discovered in mammary tumor cells but was also found in HCT116 colon, A498 renal and MiaPaca2 pancreatic and multiple NSCLC cells, including the July 2015 ERBB3-dependent ADOR isolate." (PMID 27379204, 2016). "To assess the cytotoxic activity of biparatopic DARPins in vitro, we treated a panel of ErbB2-overexpressing breast cancer cell lines (BT474, HCC1419, HCC2218, SKBR3, AU565 and ZR75-30) with wild-type PI3K activity and a range of EGFR, ErbB3 and PTEN expression levels." (PMID 27255951, 2016). "Silencing the expression of P-Rex1 from breast cancer cells largely impairs the elevation in Rac-GTP levels in response to growth factors such as EGF (ErbB1/EGFR ligand) and heregulin/neuregulin-1 (HRG, ErbB3/ErbB4 ligand), drastically affecting the motile capacity of these cells." (PMID 27351228, 2016). "Our results predict that MAPK pathway-activating mutations (such as KRASG12V) may be genetic mechanisms of resistance to HER2-direted therapy in indications outside of breast cancer, with higher EGFR and lower ERBB3 and CDKN1B expression." (PMID 27035903, 2016). "Consistent with molecular profiles of the cell lines, in all 10 indications with significant numbers of HER2+ samples, EGFR expression was relatively higher and/or ERBB3 and CDKN1B lower in in comparison to breast cancers, and these patterns hold for both the HER2+ and HER2- subsets." (PMID 27035903, 2016). "We identified an inverse correlation between miR-143/145 levels and ERBB3 protein levels, but not between miR-143/145 levels and ERBB3 mRNA levels, in breast cancer tissue samples." (PMID 25248370, 2014). "After measuring the expression levels of miR-143/145 and ERBB3 in human breast cancer tissue and paired noncancerous tissue, we detected an inverse correlation between miR-143/145 levels and ERBB3 protein levels." (PMID 25248370, 2014). "After measuring the protein levels of ERBB3 in six pairs of breast cancer tissues and corresponding noncancerous tissues, we found that ERBB3 protein levels were dramatically higher in the breast cancer tissues." (PMID 25248370, 2014).
breast cancer (continued). "ErbB3 may be considered as a valuable biomarker to predict the efficacy of EGFR- and/or erbB2-targeted therapy in the treatment of NSCLC and erbB2+ breast cancer, respectively." (PMID 24886126, 2014). "It will be interesting to explore the role of ERBB3 on NFκB in claudin-low cells and EMT, especially given our findings with EGFR in EMT cells and the known interactions among ERBB family members in breast cancer." (PMID 25252859, 2014). "In erbB2+ breast cancer tissues, preferential phosphorylation of erbB3, but not EGFR, has been observed." (PMID 24886126, 2014). "In this study, we found that ERBB3 protein levels, but not mRNA levels, were upregulated in breast cancer tissues in comparison to adjacent noncancerous tissues." (PMID 25248370, 2014). "Albeit miR-125b has been demonstrated to be tumor suppressor in breast cancer by down-regulating ERBB2 and ERBB3, several studies have showed its property to increase resistance of cancer cells, including breast cancer cells, to anticancer drug, resulting in subsequent recurrence and metastasis." (PMID 23321005, 2013). "Taken together, ErbB3 contributed to the HRG-β1-induced EMT process and cell migration through phospho-Smad2-mediated expression of Snail via the PI3k/Akt signaling pathway in SK-BR-3 and MCF7 breast cancer cells." (PMID 23937725, 2013). "On this basis, HRG-β1/ErbB3 signaling induced EMT in the SK-BR-3 and MCF7 breast cancer cell lines." (PMID 23937725, 2013). "In this study, we investigated whether HRG-β1/ErbB3 induces the process of EMT with involvement of Smad2 activation in the ErbB2-overexpressing SK-BR-3 cell line and luminal A breast cancer cell line MCF7." (PMID 23937725, 2013). "In murine fibroblasts, C3H10T1/2, and human breast cancer cells, MDA-MB-361, where high levels of expression of erbB2 (naturally overexpressed) and erbB3 (ectopically or naturally overexpressed) are evident, mutual interaction between erbB2 and erbB3 takes place." (PMID 23702846, 2013). "ERBB3 is overexpressed in approximately 22% of breast cancer cases, and 25% of cases are reported as being ERBB3-negative." (PMID 23088371, 2012). "For example, Scott and colleagues reported that miR-125a and miR-125b could reduce invasion and migration capacity of SKBR3 breast cancer cells through targeting ERBB2 and ERBB3 genes." (PMID 20932331, 2010). "While there is some evidence suggesting that HER receptor signaling may influence ferroptosis in other cancer types, such as breast cancer or melanoma, no studies to date have explored the potential link between ERBB3 and ferroptosis in gastric cancer." (PMID 40846695, 2025). "The identification of only two known or likely breast cancer driver mutations (GATA3 and ERBB3) in two of the specimen was not surprising, as these specimens represent pure PML lacking any invasive component, and thus should bear less genomic resemblance to breast cancer." (PMID 33208147, 2020). "Also, no mutations were detected for other described breast cancer‐associated genes (e.g., RAD51, RAD50, p27, ESR1/2, ERBB2, ERBB3, AKT1, CCDN1, FGFR1, MYC, and RB1) in any of the tissues or the CTC cell line." (PMID 32667137, 2020). "A combination of three proteins comprising the receptors EGFR, ERBB3/HER3, and the cyclin-dependent kinase inhibitor p27 (CDKN1B) was found to be a potential biomarker for dependence on PI3K/AKT vs. MAPK/ERK signaling for drug resistance in HER2 breast cancers." (PMID 35582587, 2019). "Indeed, our data showed that co-expression of miR-125a and miR-205 was more potent than either miRNA alone to inhibit erbB3 expression, decrease the levels of p-HER3, p-Src, p-Akt, and E2F1, and induce expression of p27kip1 in HER2-overexpressing breast cancer cells." (PMID 30093840, 2018).